CASP9 (caspase 9)
Diseases named in the same sentence as CASP9 in open-access papers (continued):
Sharing a sentence is not in itself a finding about the gene and the disease.
prostate carcinoma (73 papers, 2003 to 2026). A carcinoma that arises from epithelial cells of the prostate gland. "Embelin was previously identified as a small molecular inhibitor of the X-linked inhibitor of apoptosis proteins that can cause cell death through activating caspase-9 and subsequent cell apoptosis in prostate cancer cells with high levels of XIAP." (PMID 31635287, 2019). "Our meta-analysis suggests that the caspase 9 rs4645978 most likely contributes to decreased susceptibility to cancer in Caucasians and prostate cancer." (PMID 22616010, 2012). "Our study found a significantly protective effect of CASP9 G variant in rs4645978 in the subgroups of Caucasians and prostate cancers." (PMID 22616010, 2012). "In summary, this meta-analysis supports that the caspase 9 rs4645978 most likely contributes to decreased susceptibility to cancer in Caucasians and prostate cancer." (PMID 22616010, 2012). "Moreover, downregulation of GRP94 in prostate cancer cells can cause upregulation of cleaved caspase-9 and Bax expression levels, while suppression of Bcl-2 and Vimentin expression levels can induce apoptosis and inhibition of prostate cancer cell invasion." (PMID 38649679, 2024). "Genistein may up-regulate the expression of the tumor suppressor miR-574-3p in clinical prostate cancer samples and prostate cancer cell lines, thereby causing apoptosis through Bcl-xL, caspase-9 and caspase-3 pathways regulation." (PMID 36829927, 2023). "In DU145 prostate cancer cells, it upregulates Bax expression, facilitates cytochrome c release, and initiates the caspase-9/caspase-3 signaling cascade." (PMID 41234537, 2025). "AAP-H, a peptide derived from the sea anemone, Anthopleura anjunae, was shown to induce apoptosis in DU-145 human prostatic carcinoma cells via potential depolarization of the mitochondrial membrane and upregulation of cytochrome c, caspase-3, and caspase-9." (PMID 41034324, 2025). "KEGG pathway enrichment revealed that cancer-related pathways were widely enriched, with the Prostate cancer pathway ranking first, indicating that SR-CR AKT1, mTOR, and CASP9 were all enriched in the Prostate cancer pathway." (PMID 38326539, 2024). "The most common molecular and cellular pathway from articles reporting on the pathways and effects of UA (n = 24) in prostate cancer was caspase 3/caspase 9 (n = 10, 41.6%)." (PMID 37776274, 2024). "An oligopeptide isolated from Anthopleura anjunae was reported to induce apoptosis in prostate cancer cells, with the apoptotic cells showing an increase in Pro-apoptotic proteins, such as Bax, cytochrome-C, caspase-3, and caspase-9." (PMID 38535323, 2024). "To investigate the role of HIST3H2A in regulating the proliferation of prostate cancer cells, we examined the expression of apoptosis-related proteins Caspase 9, Bax, and Bcl-2." (PMID 38684944, 2024). "UNC5B-AS1 is a novel lncRNA related to the malignant progression of prostate cancer and can directly target downstream caspase-9, which is a key molecule in the tumor pathway." (PMID 38228673, 2024). "Treatment of prostate cancer LNCaP with 50 μM of 20(S)-25-methoxyl-dammarane-3β,12β,20-triol for 24 h led to activation of caspase-8 and caspase-9." (PMID 39274939, 2024). "Another research revealed that HAX-1 suppresses the programmed cell death of prostate carcinoma cells via inhibiting the activation of caspase-9." (PMID 35602302, 2022). "Only VitD-dgVDBP activated caspase-3 (8%), caspase-9 (13%), and cytochrome-C (11%) on prostatic cancer cells." (PMID 35892685, 2022). "Knockdown of PVT1 in prostate cancer cell lines has been shown to increase the abundance of activated cleaved caspase-9 and -3 proteins and to induce cell apoptosis." (PMID 33430890, 2021). "In prostate cancer cells, miR-205 enhances cisplatin toxicity through the induction of cleaved caspase-9 and cytochrome c." (PMID 33406670, 2021).
prostate carcinoma (continued). "Both the catechin extracts and nanoemulsions were effective in inhibiting the growth of prostate cancer cells DU-145 through activation of caspase-9, caspase-8 and caspase-3, with the cell cycle arrest at S and G2/M phases." (PMID 34071530, 2021). "Further experimental verification showed that the expression of caspase-3 and caspase-9 protein in prostate cancer tissue was low." (PMID 35342388, 2021). "Both lovastatin and simvastatin induced activation of caspase-8, caspase-3, and caspase-9 in prostate cancer cells." (PMID 29523174, 2018). "A recent report also revealed a unique apoptotic pathway in which antagonism of Bcl-2 family members in caspase-9-inhibited prostate cancer cells triggers caspase-8-dependent apoptosis." (PMID 30429828, 2018). "Recent study also displayed that apoptosis in prostate cancer is suppressed by inhibition of caspase-9." (PMID 28177918, 2017). "The present results revealed that the treatment of prostate cancer cells with Shikonin led to the activation of caspase-9, caspase-3, and PARP." (PMID 25879420, 2015). "An activation or upregulation of caspase-9 was detected in models of esophageal and prostate cancer." (PMID 25568670, 2014). "The effect of ABT-263/caspase-9 inhibitor co-treatment on apoptosis was also examined in several other prostate cancer cell lines." (PMID 25333266, 2014). "Nevertheless, these lines of evidence reveal that treatment of caspase-9-inhibited prostate cancer cells with ABT-263 can trigger apoptosis mainly through activation of caspase-8." (PMID 25333266, 2014). "In prostate cancer activation of caspase-8 following TRD treatment was described but subsequent to activation of caspase-9." (PMID 25568670, 2014). "NU9056 treatment inhibited cellular proliferation in a panel of prostate cancer cell lines (50% growth inhibition, 8–27 μM) and induced apoptosis via activation of caspase 3 and caspase 9 in a concentration- and time-dependent manner." (PMID 23056207, 2012). "Recent reports have revealed the involvement of JNK-mediated Bcl-2 phosphorylation and degradation, and also the activation of caspase-9 in the apoptosis of both the androgen-dependent and -independent human prostate cancer cells." (PMID 21504622, 2011). "Resveratrol-induced apoptosis engages mitochondria, as was shown by a drop in mitochondrial membrane potential and activation of caspase-3 and caspase-9 in both prostate cancer PC-3 and LNCaP cells." (PMID 21209944, 2010). "Curcumin-induced apoptosis engages mitochondria, which was evident by drop in mitochondrial membrane potential and activation of caspase-3 and caspase-9 in both prostate cancer PC-3 and LNCaP cells." (PMID 18226269, 2008). "Activation of initiator caspase-9 after exposure to TRAIL or IR was reported in carcinomas of the prostate and lung, Ewing's sarcoma and Jurkat lymphoma cells." (PMID 12771998, 2003). "AKT1, mTOR, and CASP9 were all located at the core of the Prostate cancer signaling pathway." (PMID 38326539, 2024). "Moreover, zinc reduces hypoxia-inducible factor-1α in prostate cancer cells and can have apoptotic effects by activating caspase-3 and caspase-9, and increasing levels of Bax protein, a pro-apoptotic protein; hence elevating the Bax/Bcl-2 ratio." (PMID 38507438, 2024). "In particular, CASP9 has been found to be enriched in the Prostate cancer pathway." (PMID 38326539, 2024). "The down-regulation of AKT1 and mTOR expression and the up-regulation of CASP9 expression implied that the conduction of the Prostate cancer signaling pathway is blocked, then this pathway-mediated proliferation was stalled and apoptosis was significantly increased." (PMID 38326539, 2024).
prostate carcinoma (continued). "Moreover, supporting mitochondrial-dependent apoptosis cascade activation, robust caspase-3 and caspase-9 activation in SKI-178-treated prostate cancer cells was detected." (PMID 37604912, 2023). "Thus, treatment with AE increased the activities of caspase-9 and -3 in a dose-dependent manner in prostate cancer cells." (PMID 38348349, 2023). "Agarwal and colleagues have also found that the combination of the Jak1 inhibitor and silibinin (an active constituent of silymarin) is able to reduce STAT3 phosphorylation and to activate caspase-9 and caspase-3, thus leading to the apoptosis of prostate cancer DU145 cells." (PMID 33299414, 2020). "Furthermore, the co-downregulation of GRP78 and GRP94 expressions in prostate cancer cells by their specific siRNAs suppressed cell migration and promoted caspase-9-dependent apoptosis." (PMID 32748834, 2020). "Upon incubation with 9F7-F11, we observed BID cleavage and BIM expression also in DU145 prostate cancer cells, which are BAX-deficient but express BAK that could replace BAX to induce caspase-9 activation." (PMID 31443721, 2019). "In addition, it also activates apoptosis by the activation of both intrinsic (caspase-9) and extrinsic (caspase-8) apoptotic pathways in prostate cancer cells." (PMID 30563284, 2018). "Thus, by preventing XIAP interaction with caspase-9, it allowed the activation of initiator caspase-9 in prostate cancer cells, which led to apoptosis." (PMID 29686719, 2018). "Moreover, also docetaxel was shown to enhance TRAIL-induced apoptosis through caspase-8, caspase-9 and caspase-3 activation in different prostate cancer cell lines." (PMID 28758908, 2017). "Additionally, we uncovered a unique apoptotic pathway in which ABT-263 and caspase-9 inhibition paradoxically promote apoptosis in human prostate cancer cells, despite the fact that ABT-263 activates caspase-9." (PMID 25333266, 2014). "Saffron extract (SE) showed dose and time-dependent antiproliferative effect on 5 different malignant prostate cancer cell lines (IC50 = 0.4–4 mg/mL), by arresting cells at G0/G1 phase and caused apoptosis through strikingly downregulation of Bcl-2 expression, activation of caspase-9." (PMID 31261861, 2019). "Similarly, pretreatment with caspase-9 and caspase-3 inhibitors or the ER stress inhibitor Salubrinal significantly inhibited the Shikonin induced caspase activation in DU-145 and PC-3 prostate cancer cells." (PMID 25879420, 2015). "This study showed that combination treatment of prostate cancer cells with docetaxel and d-limonene can overcome the resistance of prostate cancer cells to apoptosis and that the generation of ROS, activation of caspase-9 and caspase-3 may play a role in enhanced cytotoxicity." (PMID 19465777, 2009). "SR-CR inhibited the Prostate cancer signaling pathway by downregulating the expression of AKT1 and mTOR, and upregulating CASP9, leading to apoptosis in prostate cancer cells." (PMID 38326539, 2024). "AKT1, mTOR, CASP9, and BCL2 were identified as the top targets involved in the anti-prostate cancer resistance effect of the SR-CR drug pair." (PMID 38326539, 2024). "Mechanistic studies showed that Co-Sp reduced the expression of cyclin D1, cyclin E, CDK4, CDK2, MMP-9, MMP-1, and Bcl-2, and increased the expression of p21, cleaved caspase-9, cleaved caspase-3, cleaved PARP, and Bax in prostate cancer cells." (PMID 37313467, 2023). "In another study, expression of cleaved caspase-9 and cleaved caspase-3 was upregulated by RBM5 in prostate cancer." (PMID 28061901, 2017). "CT exerted cytotoxicity against prostate cancer cells such as LNCaP, PC-3, and DU145 cells in a concentration-dependent manner and activated caspase 9/3 and PARP cleavage, implying mitochondrial-dependent apoptosis in PC-3 cells under normoxia or hypoxia." (PMID 23243443, 2012).
prostate carcinoma (continued). "We found that saposin C, in a dose-dependent manner, increased procaspase-3 and PARP levels and decreased the cleaved form of caspase-9 and -3 and PARP (a caspase-3 substrate) in both AS and AI prostate cancer cells." (PMID 15548330, 2004). "XHP could activate the cleave caspase-3 and caspase-9 protein and mRNA of the PC3 prostate cancer subcutaneous transplantation significantly, compared to the control group, p = 0.002." (PMID 35342388, 2021). "Our findings are consistent with a previous study showing that EEOS effectively induced apoptosis in human prostate cancer cells (LNCaP) through the down-regulation of BCL-2 and significant elevation of Caspase-9 and Caspase-3 activities in a dose-dependent manner." (PMID 34440988, 2021). "In a previous study, Tsai and Chen prepared a highly stable catechin nanoemulsion from green tea leaf waste and reported that it was effective in inhibiting the growth of prostate cancer cells PC-3 with the IC50 being 8.5 μg/mL through activation of caspase-8, caspase-9 and caspase-3." (PMID 34071530, 2021). "Serratia marcescens, which belongs to facultative anaerobes, can inhibit the growth of prostate cancer cells by down-regulating IAP family inhibitors XIAP, CIAP-1, and CIAP-2, activating caspase-9 and caspase-3, and this is accompanied by the degradation of poly-ADP-ribose polymerase." (PMID 34956913, 2021). "However, studies on lung, prostate cancer and AML failed to reveal association of CASP9 -293 del polymorphism with cancer risk." (PMID 34530993, 2019). "In prostate cancer cells, however, evodiamine caused an elevation in the activities of caspase-3 and caspase-9, but not caspase-8, in PC3 and LNCaP cells; and of caspase-3, caspase-9, and caspase-8 in DU145 cells." (PMID 29690562, 2018). "Given that apoptosis can also be induced in human prostate cancer cells via the interaction of Fas and FasL, we examined the involvement of this pathway in the augmented, caspase-8-dependent apoptosis of PC3 cells co-treated with ABT-263 and the caspase-9 inhibitor." (PMID 25333266, 2014). "Embelin treatment of PC3 prostate cancer cells did not decrease XIAP protein levels, and did not increase caspase 9 activation (alone or combined with ionizing radiation) although there was an increase in annexin V and propidium iodide double-positive cells." (PMID 24603802, 2014).
gastric cancer (71 papers, 2009 to 2025). A primary or metastatic malignant neoplasm involving the stomach. "In addition, overexpression of UL138 greatly induced apoptotic cell death in different gastric cancer cells, in association with increased cleavage of apoptotic proteins caspase-3 and caspase-9 and reduction of an anti-apoptotic protein Bcl-2." (PMID 26735338, 2016). "major compounds involved a lower Bcl-2/Bax ratio and upregulation of CASP3 and CASP9 levels, highlighting significant differences in anti-gastric cancer activity between extracts prepared from fresh versus dried P. japonicus var." (PMID 40573220, 2025). "Apoptosis of gastric cancer cells is induced by the activation of two key apoptotic pathways, caspase-9 and caspase-3.Deguelin demonstrated IC50 values of 11.83μM and 9.33 μM in MGC-803 and MKN-45 cells, respectively, after 72 h of treatment." (PMID 40672375, 2025). "In our study, αCLDN18.2-MMAE, an ADC composed of an anti-CLDN18.2 monoclonal antibody and the tubulin inhibitor MMAE, induced a dose-dependent apoptosis via the cleavage of caspase-9/PARP proteins in CLDN18.2-positive gastric cancer cells." (PMID 39227365, 2024). "In the study of cisplatin-resistant gastric cancer, it was found that exosome transmitted miR-769-5p conferred cisplatin resistance and progression in gastric cancer by targeting CASP9 and promoting ubiquitination degradation of p5347." (PMID 38730240, 2024). "We also confirmed that monotherapy as well as combination therapy based on Les-4367 and anti-HER2 monoclonal antibodies led to the activation of caspase-9 in AGS gastric cancer cells." (PMID 37047765, 2023). "Decreased cell viability of gastric cancer cells by evodiamine treatment was mediated by activation of caspase-3, caspase-7, caspase-8, and caspase-9; cleavage of PARP; and subsequent induction of apoptosis." (PMID 36135210, 2022). "HSP-treated gastric cancer inhibited cell proliferation by inducing apoptosis by increasing Bax/Bcl-2 ratio, cyt-c,caspase-3, caspase-9, AIF, and Apaf-1 via a mitochondrial-dependent pathway in vitro and xenograft tumours at a dose-dependent manner." (PMID 35128104, 2022). "According to previous in vitro studies, the cell-free culture supernatant of Lactiplantibacillus plantarum exhibited cytotoxicity and apoptosis activity through regulation of Bax, caspase-3, and caspase-9 in gastric cancer AGS cells." (PMID 36077182, 2022). "Flow cytometry was used to determine caspase-8 and caspase-9 activity in gastric cancer cells after 24 and 48 h of incubation with the tested compounds." (PMID 34770912, 2021). "For example, exosomes secreted by gastric cancer cells transfer miR-15b-3p to recipient gastric cancer cells, promoting the progression of gastric cancer through the dynein light chain Tctex-type 1/caspase-3/caspase-9 signaling pathway." (PMID 33267910, 2020). "Z-VAD-FMK inhibited the increases in cleaved PARP, cleaved caspase 3, cleaved caspase 8, and cleaved caspase 9 protein levels, indicating that Genipin enhances apoptosis in gastric cancer cells." (PMID 31351462, 2019). "In the present study, we found that UA significantly inhibited cell growth and induced apoptosis via increasing the protein levels of cleaved-PARP and cleaved-caspase 9 in gastric cancer cells." (PMID 31547587, 2019). "All the compounds tested increased the expression of initiator caspase-9 in a dose dependent manner in gastric cancer cells in comparison with control." (PMID 29549610, 2018).